MINCR (MYC-induced long non-coding RNA)
Synonyms: TCONS_00015189; LINC01604
Gene: Long non-coding RNA gene on chromosome 8 (143,280,147 to 143,281,713, reverse strand). Ensembl gene ENSG00000253716.
Diseases named in the same sentence as MINCR in open-access papers:
MINCR is named in the same sentence as 33 diseases in open-access papers, as found by Europe PMC text mining. Sharing a sentence is not in itself a finding about the gene and the disease. The quoted sentences say what the papers report.
gallbladder cancer (5 papers, 2019 to 2023). "Recent studies have showed that lncRNA MINCR plays oncogenic roles in cancers, such as gallbladder cancer and hepatocellular carcinoma." (PMID 31481083, 2019). "After that, MINCR was found to be significantly increased, and play an oncogenic role in cancers, such as gallbladder cancer and hepatocellular carcinoma." (PMID 31481083, 2019). "Moreover, MINCR is also overexpressed in hepatocellular carcinoma and gall bladder cancer, and its overexpression promotes cell proliferation, migration, and invasion." (PMID 36741910, 2023). "According to some studies, MINCR dysregulation could be a parameter affecting the development of the human cancers, such as gallbladder cancer and hepatocellular carcinoma." (PMID 34923811, 2022). "For example, MINCR upregulates the expression of EZH2 by sponging miR-26a, which further enhances the MYC/miRNA/EZH2 axis in gallbladder cancer." (PMID 37215074, 2023). "Moreover, MINCR can also promote EMT progression of tumors, such as gallbladder cancer, colorectal cancer, and oral squamous cell carcinoma." (PMID 37215074, 2023).
hepatocellular carcinoma (5 papers, 2019 to 2023). A malignant tumor that arises from hepatocytes. "MINCR was highly expressed in nasopharyngeal, colon, non-small cell lung cancers, and hepatocellular carcinoma and promotes cancer development." (PMID 35910212, 2022). "The lncRNA MINCR is overexpressed in some cancers such as colon cancer, hepatocellular carcinoma, and non-small cell lung cancer, in which it has been suggested as a potential diagnostic and prognostic biomarker." (PMID 35632705, 2022). "Moreover, MINCR can also regulate the Wnt/β-catenin signaling pathway by sponging miR-107 in hepatocellular cancer." (PMID 37215074, 2023).
colon cancer (4 papers, 2022 to 2024). "For example, MINCR aggravates colon cancer and glioma via the miR-708-5p-mediated Wnt/β-catenin pathway and miR-876-5p/GSPT1 axis, respectively." (PMID 36741910, 2023). "For example, MINCR uses miR-708-5p to upregulate CTNNB1 and activate the Wnt/β-catenin pathway, thereby promoting colon cancer development." (PMID 38714724, 2024).
lung carcinoma (4 papers, 2019 to 2023). "The expression of MINCR in clinical lung cancers, including LUAD and LUSC, was first identified using TCGA dataset." (PMID 31481083, 2019). "Furthermore, MINCR expression in the lung cancer and para-tumor tissues from 29 NSCLC patients was examined." (PMID 31481083, 2019).
colorectal cancer (3 papers, 2020 to 2023). A primary or metastatic malignant neoplasm that affects the colon or rectum. "It has also been reported that, in NSCLC and colorectal cancer, MINCR overexpression promotes cell proliferation and decreases apoptosis." (PMID 35632705, 2022).
glioma (3 papers, 2022 to 2023). A benign or malignant brain and spinal cord tumor that arises from glial cells (astrocytes, oligodendrocytes, ependymal cells). "Taken collectively, these findings indicate that the MINCR/miR-876-5p/GSPT1 axis plays a vital role in glioma development and progression." (PMID 37215074, 2023). "In the Amyotrophic Lateral Sclerosis, MINCR was downregulation while upregulation in glioma patients." (PMID 37215074, 2023). "And, the knockdown of MINCR expression inhibits cell proliferation, migration, and invasion and promotes apoptosis of glioma cell lines." (PMID 37215074, 2023). "Furthermore, MINCR negatively regulates and sponges miR-876-5p to control GSPT1 expression in glioma tissues and cell lines." (PMID 37215074, 2023). "Increased expression of LINC00473 in HNSCC; LINC00114, MINCR and PVT1 in NPC; Linc-RA1 in glioma; LINC00473and CYTOR in NSCLC; NEAT1 and LINC00958 in cervical cancer; H19 in cardiac cancer; LINC02582 in breast cancer; and TUG1 in bladder cancer were associated with radioresistance." (PMID 36323697, 2022).
bladder cancer (2 papers, 2022). "For example, in bladder cancer cells, MINCR regulates the expression of EZH2 through miR-26a-5p, while silencing MINCR decreases cell proliferation and invasion and increases apoptosis." (PMID 35632705, 2022).
cervical cancer (2 papers, 2022). A primary or metastatic malignant neoplasm involving the cervix. "The role of the lncRNA MINCR in cervical cancer and its relationship with variants of oncogenic HPV remain unknown." (PMID 35632705, 2022). "However, the role of MINCR in cervical cancer and its relationship with the variants of oncogenic HPV remain unknown; therefore, the objective of this study was to analyze the effect of the E6 oncoprotein of the AA-c variant of HPV16 on the expression of RAP1B through the lncRNA MINCR." (PMID 35632705, 2022).
osteosarcoma (2 papers, 2020 to 2023). A usually aggressive malignant bone-forming mesenchymal neoplasm, predominantly affecting adolescents and young adults. "In osteosarcoma, the knockdown of MINCR inhibited cell proliferation and migration and promoted apoptosis." (PMID 37215074, 2023). "Furthermore, c-Myc and cell cycle-related genes were downregulated after knockdown of MINCR expression in osteosarcoma cells." (PMID 37215074, 2023).
Burkitt lymphoma (1 paper, 2019). A rare form of malignant mature B-cell non-Hodgkin lymphoma. "Since MINCR is a MYC-induced lncRNA, and has been reported to modulate c-Myc’s transcriptional network in Burkitt lymphoma cells, we sought to determine whether the function of MINCR may associated with the expression of c-Myc and its downstream genes." (PMID 31481083, 2019). "Since MINCR was reported to be a modulator of the c-Myc transcriptional network in Burkitt lymphoma cells, we postulated that the function of MINCR in NSCLC may be associated with its regulation of c-Myc expression." (PMID 31481083, 2019).
colorectal tumors (1 paper, 2022). "In this study, the tissue expressions of lncRNA MINCR and EZH2 mRNA between colorectal tumors and polyps were compared with the adjacent normal tissues collected from 114 Iranian patients, using real-time PCR method." (PMID 34923811, 2022).
lung injury (1 paper, 2023). "In LPS-induced acute lung injury, MINCR was overexpressed in a LPS time- and dose-dependent manner and depression of MINCR could reduce inflammatory infiltration by miR-146b-5p/TRAF6 axis." (PMID 37215074, 2023).
lymph node metastasis (1 paper, 2023). "Not only that, some studies also reported that MINCR has also been associated with lymph node metastasis and even distant metastasis." (PMID 37215074, 2023). "Moreover, MINCR expression is associated with the clinicopathological features of OSCC patients such as TMN stage, lymph node metastasis, and distant metastasis." (PMID 37215074, 2023). "In addition, high MINCR expression is correlated with high TNM classification (III–IV), low histologic grade, lymph node metastasis, and cirrhosis." (PMID 37215074, 2023).
lymphoma (1 paper, 2022). A malignant (clonal) proliferation of B- lymphocytes or T- lymphocytes which involves the lymph nodes, bone marrow and/or extranodal sites. "LncRNAs such as MINCR may essentially contribute to both MYC-positive lymphomas and numerous types of MYC-dependent cancers." (PMID 34923811, 2022). "MINCR, known as an lncRNA, has been related to the MYC expression in MYC-positive lymphomas." (PMID 34923811, 2022).
nasopharyngeal carcinoma (1 paper, 2022). A carcinoma arising from the nasopharyngeal epithelium. "In nasopharyngeal cancer, lncRNA MINCR upregulated radioresistance via miR-223/ZEB1, and ZEB1 (zinc finger E-box binding homeobox 1) drives the induction of EMT by activating stem cell characteristics, immune evasion, and epigenetic reprogramming." (PMID 35600868, 2022).
osteoarthritis (1 paper, 2023). A noninflammatory degenerative joint disease occurring chiefly in older persons, characterized by degeneration of the articular cartilage, hypertrophy of bone at the margins and changes in the synovial membrane. "While MINCR was downregulated in osteoarthritis (OA) and IL-1β induced chondrocytes." (PMID 37215074, 2023). "Furthermore, we have summarized the regulatory mechanisms of MINCR in other diseases such as osteoarthritis, neurodegeneration, and schizophrenia." (PMID 37215074, 2023).
pancreatic adenocarcinoma (1 paper, 2022). "A negative correlation between the expression of MINCR and miR-28-5p in patients with pancreatic adenocarcinoma was found, suggesting the role of MINCR as a ceRNA for miR-28-5p." (PMID 35632705, 2022).
polyp (1 paper, 2022). A usually exophytic mass attached to the underlying tissue by a broad base or a thin stalk. "In our study, there had been an association between the high expression of MINCR and EZH2 with the type of samples (tumor and polyp) and clinical stage." (PMID 34923811, 2022).
schizophrenia (1 paper, 2023). A major psychotic disorder characterized by abnormalities in the perception or expression of reality. "Another study showed MINCR was identified as a vital gene in the lncRNA-miRNA network of schizophrenia." (PMID 37215074, 2023).
squamous cell carcinoma (1 paper, 2023). A carcinoma arising from squamous epithelial cells. "In the published articles, MINCR has been shown to be overexpressed in various tumors, whether adenocarcinoma or squamous cell carcinoma." (PMID 37215074, 2023).
cancer (13 papers, 2019 to 2023). A tumor composed of atypical neoplastic, often pleomorphic cells that invade other tissues. "The lncRNA MINCR has been demonstrated to be overexpressed in different cancers and to be significantly associated with the expression of the oncogene MYC." (PMID 37215074, 2023). "MINCR is upregulated in cancer tissues and has an association with the survival rate, cell migration, and invasion in tumor tissues." (PMID 34923811, 2022). "The overexpression of MINCR could trigger cancer-related gene alterations, causing disruptions in the cell cycle and growth factor signaling." (PMID 36741910, 2023). "Our analysis of the literature suggests that MINCR has potential as a novel biomarker and therapeutic target in human cancers." (PMID 37215074, 2023). "In this review, we summarize the latest research on MINCR, as well as its aberrant expression, clinical significance, and regulatory mechanism in different cancers." (PMID 37215074, 2023). "MINCR is involved in cancer development by regulating cell cycle-related genes such as AURKA, AURKB, and CDK2." (PMID 37215074, 2023). "It is possible that MINCR functions with other non-coding RNAs to regulate the same miRNA in disease, thereby altering the targeted miRNAs in different cancers." (PMID 37215074, 2023). "Mechanically, MINCR acts an oncogene in cancers via regulating MYC, targeting miRNAs, and mediating Wnt/β-catenin signaling pathways." (PMID 37215074, 2023). "In this review, we summarize and analyze the oncogenic roles of MINCR in a variety of human cancers in terms of its clinical significance, biological functions, cellular activities, and regulatory mechanism." (PMID 37215074, 2023). "The role of MINCR has been studied in some types of cancer, where it has been found to inhibit the activity of some miRNAs through the ceRNA function." (PMID 35632705, 2022). "Since its identification and characterization, several studies have reported that MINCR can regulate multiple cancer phenomena, including cell proliferation, cell cycle regulation, apoptosis, migration, invasion, and the epithelial-to-mesenchymal transition (EMT)." (PMID 37215074, 2023). "Moreover, MINCR has been reported to act as a biomarker in the prognosis of patients with different cancers." (PMID 37215074, 2023). "Importantly, MINCR knockdown decreases cell migration by almost 50%, which is consistent with reports for other types of cancer." (PMID 35632705, 2022). "MINCR is a Myc-induced lncRNA related to some cancers via acting as a ceRNA59." (PMID 34952924, 2021). "MINCR expression was significantly increased in cancer tissues compared with para-tumor tissues." (PMID 31481083, 2019). "All these studies imply that MINCR could be a therapeutic target as well as prognostic marker for cancer treatment." (PMID 31481083, 2019). "Nonetheless, the exact mechanism of MINCR function in cancer development is still largely unknown." (PMID 34923811, 2022). "The upregulation of MINCR may participate in cancer initiation via triggering the EZH2 expression." (PMID 34923811, 2022). "The knockdown of MINCR inhibits cell proliferation and invasion by inhibiting the Wnt/β-catenin pathway in OSCC, similar to other human cancers." (PMID 37215074, 2023). "Systematically, findings have signified that MINCR/EZH2 axis contributes to the rapid growth of the cells, cell invasion, and also apoptosis in the cancer cells." (PMID 34923811, 2022). "We herein explored that MINCR may exert oncogenic effects in CRC and can be used as a potential biomarker for the detection of this cancer." (PMID 34923811, 2022).
tumor (6 papers, 2019 to 2023). "We also investigated the association of the MINCR expression in the tumor tissue samples with clinicopathological characteristics." (PMID 34923811, 2022). "MINCR expression is significantly elevated in GBC tissues, being associated with larger tumor size, lymph node metastasis, and shorter overall survival time, which suggests that MINCR is related to poor prognosis in GBC patients." (PMID 34575316, 2021). "After analyzing the expression of MINCR in 70 pairs of HCC tumor tissues and adjacent normal tissues, it was demonstrated that the MINCR level is elevated in tumor tissues, consistent with the results of other studies." (PMID 37215074, 2023). "Consistent with this, MINCR has also been shown to promote tumor migration and invasion at the cellular level." (PMID 37215074, 2023). "According to the relative MINCR expression ratio (2.42) in the tumor tissue, MINCR demonstrated a significant upregulation in the CRC tissue as compared to the neighboring normal CRC tissues." (PMID 34923811, 2022). "In the present research, the expression level of MINCR in tumor and polyp tissue samples was evaluated." (PMID 34923811, 2022). "The high expression of the MINCR has been correlated with the size of the tumor, node, and metastasis stage." (PMID 34923811, 2022). "Results showed a higher expression level of MINCR in the tumor and polyp tissues in comparison to the neighboring normal tissues." (PMID 34923811, 2022). "miRNA sets were analyzed in several tumor samples obtained from the TCGA database to correlate their expression levels with the levels of MINCR." (PMID 35632705, 2022). "Therefore, MINCR may play a vital role in all stage of tumor." (PMID 37215074, 2023). "The qRT-PCR results showed that the relative expression level of MINCR and APCDD1L-DT were higher in 786-O and 769-P tumor cells than in HK-2 cells, which were normal renal tubular epithelial cells." (PMID 36406128, 2022). "The results indicated that the relative expression level of MINCR and APCDD1L-DT was higher in 786-O and 769-P tumor cells than that in HK-2 cells, which were normal renal tubular epithelial cells." (PMID 36406128, 2022). "The authors showed that overexpression of certain lncRNAs (e.g., MALAT1, MINCR, ROR, LINC00152, and AFAP1-AS1) can be used as potential predictors of worse survival or can be involved in the regulation of tumor size (e.g., AFAP1-AS1, MALAT1 and ROR)." (PMID 34575316, 2021). "Results showed that MINCR expression was significantly increased in LUAD and LUSC samples compared with non-tumor controls." (PMID 31481083, 2019). "In addition, MINCR expression is higher in GBC patients with larger tumor sizes, more lymph node metastatic lesions, and shorter overall survival times than in those with smaller tumor sizes, fewer lymph node metastatic lesions, and longer overall survival times." (PMID 37215074, 2023).
MINCR also shares sentences with these, for which no sentence is quoted: non-small cell lung carcinoma (3 papers); breast carcinoma (2); adenocarcinoma (1); B-cell lymphomas (1); chronic lymphocytic leukemia (1); glioblastoma (1); kidney cancer (1); mental disorder (1); oral squamous cell carcinoma (1); ovarian carcinoma (1); pancreatic endocrine neoplasm (1).